ZNF208 (zinc finger protein 208)
Description:
May be involved in transcriptional regulation.
Synonyms: PMIDP; ZNF95
Tractability: PROTAC: ubiquitination databases record sites on it.
Gene: Protein-coding gene on chromosome 19 (21,932,958 to 22,010,949, reverse strand). Ensembl gene ENSG00000160321.
Subcellular location: Nucleus
Subcellular location (Human Protein Atlas): Golgi apparatus; Cytosol
Pathways (Reactome):
Gene expression (Transcription): Generic Transcription Pathway
Gene Ontology:
Molecular function: transcription cis-regulatory region binding; zinc ion binding
Biological process: regulation of transcription by RNA polymerase II; negative regulation of transcription by RNA polymerase II; regulation of DNA-templated transcription
Cellular component: nucleus
Genetic constraint (gnomAD): Loss-of-function variants: 10 observed, 13.16 expected, observed/expected ratio (o/e) 0.76, 90% interval 0.47 to 1.29. The upper end of that interval is the gene's LOEUF score, 1.29, which puts it in group 5 of 6, group 1 being the genes least tolerant of losing a copy. Missense variants: 1,652 observed, 1,433.7 expected, observed/expected ratio (o/e) 1.15, 90% interval 1.11 to 1.2. Synonymous variants: 497 observed, 461.84 expected, observed/expected ratio (o/e) 1.08, 90% interval 1 to 1.16.
Homologues: Orthologues: chimpanzee ZNF208 (94% identical), macaque ZNF208 (52% identical), Drosophila melanogaster zf30C (14% identical), zebrafish znf646 (14% identical), zebrafish si:dkey-89b17.4 (14% identical), zebrafish znf576.1 (14% identical), Drosophila melanogaster CG18011 (13% identical), Drosophila melanogaster CG6791 (11% identical), Drosophila melanogaster hang (10% identical), Drosophila melanogaster CG30020 (10% identical), Caenorhabditis elegans ztf-15 (9% identical), Drosophila melanogaster az2 (9% identical), and 21 more. Paralogues in human: ZNF729 (55% identical), ZNF91 (52% identical), ZNF99 (46% identical), ZNF107 (45% identical), ZNF160 (31% identical), ZNF420 (28% identical), ZNF347 (28% identical), ZNF184 (27% identical), ZNF845 (26% identical), ZNF84 (26% identical), ZNF594 (25% identical), ZNF569 (25% identical), and 24 more.
Diseases named in the same sentence as ZNF208 in open-access papers:
ZNF208 is named in the same sentence as 26 diseases in open-access papers, as found by Europe PMC text mining. Sharing a sentence is not in itself a finding about the gene and the disease. The quoted sentences say what the papers report.
coronary artery disease (6 papers, 2016 to 2024). "The association of genetic polymorphism of ZNF208 with coronary artery disease (CAD) was previously discovered in a Chinese population." (PMID 35987697, 2022). "Furthermore, genome-wide association studies of adult leukocyte TL (LTL) identified 7 single-nucleotide variations (ACYP2, NAF1, OBFC1, RTEL1, TERC, TERT, ZNF208) linked with LTL that mutually project towards an increased risk for coronary artery disease." (PMID 35930283, 2022). "The rs11125529, rs7675998, rs8105767, and rs7194734 SNPs belong to the ACYP2, NAF1, ZNF208, and MPHOSPH6 genes, respectively, which were found to be associated with increasing risk of developing coronary heart disease." (PMID 38293941, 2024).
gastric cancer (4 papers, 2015 to 2023). A primary or metastatic malignant neoplasm involving the stomach. "ZNF208 is a member of the zinc finger family of proteins and its mutations were found in many cancers, such as pancreatic cancer, gastric cancer, esophageal cancer and laryngeal cancer." (PMID 36960071, 2023). "In another study of gastric cancer, the activity and mRNA expression of ZNF208 were reduced as a consequence of somatic mutations, suggesting ZNF208 has a central role in tumor suppression." (PMID 27907911, 2016). "Previous studies showed an association between the ZNF208 gene and gastric cancer." (PMID 27907911, 2016). "Some nonsynonymous mutations caused low levels of gene activity with down-regulation of mRNA expression (ZNF208, CRNN, IREB2 and ACADL), which may be crucial tumor suppressor genes for gastric cancer and may contribute to the extensive dissemination of cancer cells in abdominal cavity." (PMID 26330360, 2015).
esophageal cancer (3 papers, 2016 to 2024). A primary or metastatic malignant neoplasm involving the esophagus. "Similar to the esophageal cancer study, SNPs rs8103163 and rs7248488 in the ZNF208 gene were found to contribute to susceptibility to laryngeal cancer." (PMID 39247597, 2024). "In esophageal cancer within the Chinese Han population, a connection between genetic variants in ZNF208 and susceptibility to the disease has been identified." (PMID 39247597, 2024). "We performed a case-control study to evaluate the association between SNPs/haplotypes in the ZNF208 gene and esophageal cancer susceptibility in a Chinese Han population." (PMID 27907911, 2016). "In conclusion, our data indicate that rs2188972, rs2188971, rs8103163, and rs7248488 in the ZNF208 gene as well as the ATAA haplotype are associated with an increased risk of esophageal cancer in a Chinese Han population." (PMID 27907911, 2016). "Our data indicate that variants in ZNF208 are contribute to the susceptibility to esophageal cancer in a Chinese Han population." (PMID 27907911, 2016). "In this study, we investigated the association between single nucleotide polymorphisms (SNPs) in ZNF208 and the risk of esophageal cancer in a Chinese Han population." (PMID 27907911, 2016). "Given the limited value of analysis of a single SNP, we evaluated the association between haplotypes in the ZNF208 gene and esophageal cancer susceptibility." (PMID 27907911, 2016). "We identified associations between four SNPs in ZNF208 and esophageal cancer using a logistic regression model after adjustment for age and gender." (PMID 27907911, 2016). "Although our study has provided evidence for an association between genetic variants in ZNF208 and esophageal cancer, the results should be interpreted with caution." (PMID 27907911, 2016). "provide evidence for a correlation between SNPs in the ZNF208 gene and esophageal cancer in the Chinese Han population." (PMID 27907911, 2016). "We assessed the relationship between SNPs in the ZNF208 gene and esophageal cancer in a Chinese Han population." (PMID 27907911, 2016).
glioma (3 papers, 2015 to 2026). A benign or malignant brain and spinal cord tumor that arises from glial cells (astrocytes, oligodendrocytes, ependymal cells). "Key SNPs contributing to risk of childhood glioma included rs59294613 (POT1), rs8105767 (ZNF208), and rs7705526 (TERT), which differed from the top variants previously identified in adult glioma using the same genetic instruments." (PMID 41668119, 2026).
ischemic stroke (3 papers, 2022 to 2024). A stroke disorder caused by obstruction of blood flow to the brain, due to thrombotic (local blood clot formation) or embolic (due to a blood clot or other material traveling from another site) event. "ZNF208 polymorphisms were observed to be associated with ischemic stroke in a Chinese Han population; however, no other reports concerning its role in stroke or depression were reported." (PMID 37528851, 2023).
laryngeal carcinoma (3 papers, 2022 to 2024). Carcinoma that arises from the laryngeal epithelium. "The investigation into the association of the ZNF208 gene with various types of cancers, particularly esophageal and laryngeal cancers in the Chinese Han population, has unveiled significant findings." (PMID 39247597, 2024). "We conducted an association analysis between ZNF208 polymorphisms and laryngeal cancer (LC) risk in the Northwestern Chinese Han male." (PMID 35480322, 2022).
gastrointestinal stromal tumor (2 papers, 2016 to 2022). "There were some correlations between the expression of ZNF208 gene and the patients’ response to imatinib mesylate in another study of gastrointestinal stromal tumors." (PMID 35480322, 2022).
breast carcinoma (1 paper, 2023). "This study developed a signature featuring 8 OARGs (HLA-B, RBBP8, SPRY4, WT1, WWOX, UPRT, PELO, ZNF208) and determined its prognostic and functional implications in breast cancer patients." (PMID 36960071, 2023).
Hepatitis (1 paper, 2024). Inflammation of the liver. "In summary, our discoveries indicate that genetic variations within ZNF208 could serve as predictive markers for cancer susceptibility and hepatitis in HCC." (PMID 39247597, 2024).
hepatocellular carcinoma (1 paper, 2024). A malignant tumor that arises from hepatocytes. "However, the precise impact of ZNF208 gene polymorphisms on the progression and initiation of hepatocellular carcinoma (HCC) in the Taiwanese population has not been thoroughly explored." (PMID 39247597, 2024).
lung adenocarcinoma (1 paper, 2022). A carcinoma that arises from the lung and is characterized by the presence of malignant glandular epithelial cells. "The rs8105767 in ZNF208 has been shown to be relevant with the risk of neuroblastoma and lung adenocarcinoma." (PMID 35480322, 2022).
Stroke (1 paper, 2023). Sudden impairment of blood flow to a part of the brain due to occlusion or rupture of an artery to the brain. "After combining the mRNAs screened out via the LASSO, SVM, and RF algorithms, three diagnostic mRNAs (SPATA2, ZNF208, and YTHDC1) were identified for post-stroke depression." (PMID 37528851, 2023).
cancer (9 papers, 2015 to 2024). A tumor composed of atypical neoplastic, often pleomorphic cells that invade other tissues. "Research conducted across multiple studies reveals that specific single nucleotide polymorphisms (SNPs) within the ZNF208 gene are linked to an increased risk of these cancers, suggesting a genetic predisposition influenced by variations in this gene." (PMID 39247597, 2024). "These CNV regions encode nineteen known genes, and some of which have been shown to affect aging-related phenotypes such as the shortening of telomere length (ZNF208), the risk of cancer (FOXA1, LAMA5, ZNF716), and vascular and immune-related diseases (ARHGEF10, TOR2A, SH2D3C)." (PMID 29883365, 2018). "The SNPs rs2188971 and rs8105767 within the ZNF208 gene have been studied in the context of various cancers." (PMID 39247597, 2024). "A comprehensive understanding of the molecular pathways involved in cancer, including those influenced by genes like ZNF208, is essential for developing effective treatments." (PMID 39247597, 2024). "Especially, the research on ZNF208 gene has enriched our understanding of cancer development and prompted a series of explorations in tumor research." (PMID 35480322, 2022). "The conserved C2H2 motif is also present in ZNF208, suggesting that it may be involved in cancer development and progression." (PMID 27907911, 2016).
tumor (9 papers, 2015 to 2024). "Our study underscores the complexity of genetic influences on HCC, with ZNF208 polymorphisms potentially affecting tumor progression and patient outcomes." (PMID 39247597, 2024). "Notably, genes, such as DDX11 (12p11.21), IGLV2-18 (22q11.22), OR8G5 (11q24.2), PARP4 (13q12.12), USP10 (16q24.1), and ZNF208 (19p12), exhibited multiple mutations and demonstrated tumor-driving effects." (PMID 39711964, 2024). "For example, ZNF208 may serve as a tumor suppressor, with an epigenetic mechanism of differentiation to adenocarcinoma from ZNF208 gene silencing due to promoter hypermethylation and ZNF208 underexpression." (PMID 39273049, 2024).
ZNF208 also shares sentences with these, for which no sentence is quoted: adenocarcinoma (1 paper); chronic gastritis (1); Chronic lymphocytic leukemia (1); depression (1); ependymoma (1); liver cancer (1); lung carcinoma (1); melanoma (1); metastatic cancer (1); neuroblastoma (1); neurofibroma (1); pancreatic cancer (1).